CEBPD (CCAAT enhancer binding protein delta)
Description:
Transcription activator that recognizes two different DNA motifs: the CCAAT homology common to many promoters and the enhanced core homology common to many enhancers. Important transcription factor regulating the expression of genes involved in immune and inflammatory responses. Transcriptional activator that enhances IL6 transcription alone and as heterodimer with CEBPB.
Synonyms: NF-IL6-beta; CRP3; CELF; C/EBP-delta
Tractability: PROTAC: UniProt records ubiquitination sites on it.
Gene: Protein-coding gene on chromosome 8 (47,736,913 to 47,738,164, reverse strand). Ensembl gene ENSG00000221869.
Subcellular location: Nucleus
Subcellular location (Human Protein Atlas): Nucleoplasm
Pathways (Reactome):
Developmental Biology: Transcriptional regulation of white adipocyte differentiation
Disease: HCMV Late Events
Immune System: Interleukin-4 and Interleukin-13 signaling
Gene Ontology:
Molecular function: protein binding; sequence-specific double-stranded DNA binding; DNA-binding transcription factor activity, RNA polymerase II-specific; RNA polymerase II cis-regulatory region sequence-specific DNA binding; DNA binding; DNA-binding transcription activator activity, RNA polymerase II-specific; DNA-binding transcription factor activity; identical protein binding; transcription cis-regulatory region binding
Biological process: integrated stress response signaling; regulation of cell differentiation; regulation of transcription by RNA polymerase II; transcription by RNA polymerase II; DNA-templated transcription; positive regulation of transcription by RNA polymerase II; regulation of DNA-templated transcription
Cellular component: RNA polymerase II transcription regulator complex; chromatin; nucleoplasm; nucleus
Genetic constraint (gnomAD): Loss-of-function variants: 1 observed, 4.78 expected, observed/expected ratio (o/e) 0.21, 90% interval 0.073 to 0.99. That is too few expected variants to judge how well the gene tolerates losing a copy. Missense variants: 410 observed, 287.84 expected, observed/expected ratio (o/e) 1.42, 90% interval 1.31 to 1.55. Synonymous variants: 227 observed, 143.67 expected, observed/expected ratio (o/e) 1.58, 90% interval 1.42 to 1.76.
Homologues: Orthologues: chimpanzee CEBPD (99% identical), macaque CEBPD (99% identical), pig CEBPD (87% identical), rat Cebpd (87% identical), mouse Cebpd (86% identical), tropical clawed frog cebpd (54% identical), zebrafish cebpd (51% identical), Drosophila melanogaster slbo (20% identical), Caenorhabditis elegans zip-4 (20% identical), Caenorhabditis elegans cebp-1 (18% identical). Paralogues in human: CEBPA (39% identical), CEBPE (35% identical), CEBPB (34% identical), CEBPG (17% identical).
Diseases named in the same sentence as CEBPD in open-access papers:
CEBPD is named in the same sentence as 159 diseases in open-access papers, as found by Europe PMC text mining. Sharing a sentence is not in itself a finding about the gene and the disease. The quoted sentences say what the papers report.
breast cancer (44 papers, 2007 to 2025). A primary or metastatic malignant neoplasm involving the breast. "CEBPD is a transcription factor involved in differentiation and inflammation and is associated with a good prognosis in breast cancer." (PMID 39232464, 2024). "Previous studies elucidated that epigenetic events such as CpG island hypermethylation get involved in the silence of CEBPD and are associated with metastasis of breast cancer." (PMID 36776299, 2023). "CEBPD is often hyper-methylated and is associated with good prognosis in breast cancer and has tumor-suppressive functions in ovarian cancer." (PMID 34439745, 2021). "Comparing to the activation of CEBPD in tumor-associated stromal cells, the activation of CEBPD is insensitive in breast cancer cells because an epigenetic-mediated hypermethylation on the promoter region of CEBPD gene." (PMID 26124179, 2015). "For example, the ESR2 and MAPK1 genes in the prostate cancer prediction, and the IL6 and CEBPD in the breast cancer predictions, were associated with several chemicals for each of the diseases." (PMID 20459635, 2010). "In addition, treating breast cancer with CDDP promoted the level of CEBPD in CAFs as well as tumor-associated macrophages (TAMs) and led to chemoresistance through pentraxin 3 (PTX3)-induced invasion, metastasis, and stemness." (PMID 36776299, 2023). "In breast cancer, CEBPD reportedly links to interleukin-6 and hypoxia-inducible factor 1 signaling to promote cancer stem cell-associated phenotypes, which is a well-known factor correlated with drug resistance." (PMID 38627816, 2024). "Because of its positive interactions with cyclin D1 and cyclin E, CEBPD appears to have tumor suppressive functions in breast cancer while being reduced or undetectable in invasive/metastatic cancer and tumor promoters." (PMID 37047552, 2023). "We assessed the involvement in TNBC of CEBPD and PTX3 expression in breast cancer‐associated fibroblasts (BCAFs)." (PMID 35090088, 2022). "CEBPD has been implicated in MTOR signalling enhancement by transcriptionally suppressing FBXW7, leading to mammary tumour metastasis." (PMID 34954904, 2021). "In hepatocellular carcinoma and breast cancer, CEBPD regulates the biological behavior of tumor cells." (PMID 32997416, 2020). "CEBPD promotes the proliferation of breast cancer stem cells by activating IL‐6 and HIF‐1 in breast cancer." (PMID 32997416, 2020). "Several studies demonstrated that CEBPD expression is downregulated in breast cancer, leukemia, cervical cancer, and hepatocellular carcinoma." (PMID 28099155, 2017). "Clinically, the silencing of CEBPD has been observed in many cancers, including cervical cancer, hepatocellular carcinoma, prostate cancer, leukemia and breast cancer." (PMID 26124179, 2015). "CEBPD is a well-known transcription factor and holds dual traits as a tumor suppressor in hepatocellular carcinoma, prostate cancer cells or oncogene in lung adenocarcinoma, breast cancer and UC based on the diverse microenvironments of tumors." (PMID 35203290, 2022). "In addition, CEBPD is thought to be a potent tumor suppressor, and its expression is downregulated in several cancers, including breast cancer, leukemia, cervical cancer, and hepatocellular carcinoma." (PMID 28099155, 2017). "In addition, the E3 ubiquitin ligase, seven in absentia homolog 2 (SIAH2), was suggested to be involved in posttranslational regulation through the polyubiquitination of CEBPD and downstream degradation via the proteasome in breast cancer cells." (PMID 25591788, 2015). "Based on the analysis of scRNA-seq and bulk RNA-seq data, we built and validated a cancer fibroblast-related risk signature consisting of five genes (BGN, LUM, CCL19, CEBPD, and ID3) that may be utilized as an independent prognostic indicator for breast cancer patients." (PMID 36510567, 2022). "Therefore, an issue whether the CEBPD-induced autophagy contributes to the death of breast cancer, leukemia and cervical cancer needs to be further dissected." (PMID 28099155, 2017).
breast cancer (continued). "Another gene, CEBPD, is regulated in response to physiological inducers of ER stress; CEBPD is also a mediator of PERK signaling in chemokine production in melanoma and breast cancer." (PMID 37112622, 2023). "However, there is strong evidence that CEBPD may also promote tumor progression in breast cancer." (PMID 26307680, 2015). "Indeed, DDR1i caused differential expression in several direct RUNX1 target genes including DUT, an essential nucleotide metabolism enzyme seen upregulated across breast cancers, and MYC, along with ANP32B, PLEC, CEBPD, ID1, and STAT3." (PMID 40614729, 2025). "Over the past few years, accumulating research has identified the dual functions of CEBPD as a tumor suppressor in pancreatic ductal adenocarcinoma (PDAC), hepatocellular carcinoma, and breast cancer but an oncogene in glioblastoma and UC, relying on the tumor microenvironment and cell types." (PMID 36776299, 2023). "One recent study demonstrated that CEBPD directly inhibits expression of the tumor suppressor FBXW7, resulting in a consequent enhancement of mTOR/AKT/S6K1 signaling, which further suggests CEBPD is necessary for metastatic progression of mammary tumors." (PMID 26307680, 2015). "However, CEBPD‐associated PTX3 regulation has not been examined in detail regarding its clinical or epidemiological characteristics in various cancers, including breast cancer." (PMID 35090088, 2022). "An increase in mammary tumor multiplicity and a decrease in lung metastasis were observed in HER2/neuTg mice lacking CEBPD." (PMID 26124179, 2015).
glioblastoma (18 papers, 2015 to 2026). The most malignant astrocytic tumor (WHO grade IV). "Analyses of clinical samples and public databases demonstrated that CEBPD was significantly up-regulated in glioblastoma." (PMID 40114930, 2025). "We thus propose a model of signaling pathways in the STAT3/CEBPD/PDGFA axis mediating inflammatory factor-induced stemness in glioblastoma." (PMID 31300060, 2019). "Additionally, under anoxic conditions, CEBPD was highly expressed in glioblastoma tissues and cell lines." (PMID 40114930, 2025). "To test the hypothesis that dn-decoy forms of CEBPB and CEBPD kill cancer cells, we transfected T98G glioblastoma cells with vectors expressing myc-tagged CEBPB or CEBPD leucine zipper sequences, or tag alone." (PMID 34065488, 2021). "From this analysis, we found ten DEGs specific to IDH1-wt glioblastoma, namely, S100A11, AC091932.2, PIGH, AC020910.5, RPS8P6, AC105339.6, AL589986.1, AL049874.3, CEBPD, and Z99496.1." (PMID 37568598, 2023).
glioma (16 papers, 2016 to 2026). A benign or malignant brain and spinal cord tumor that arises from glial cells (astrocytes, oligodendrocytes, ependymal cells). "We first show that IL-1β is highly expressed in GBM, promotes glioma spheroid formation, and is associated with the elevated CEBPD expression." (PMID 31300060, 2019). "We first found that IL-1β promotes glioma spheroid formation and is associated with elevated CEBPD expression." (PMID 31300060, 2019). "In this study, we demonstrated that glioma CEBPD directly binds to and activates the promoter regions of miR-4257 and miR-3156, located within the genes ADAMTSL4 and ANKRD30BP3, respectively." (PMID 41736026, 2026). "In animal models, co-inoculation of glioma cells with antisense miR-4257 and miR-3156 or CEBPD knockdown, along with M1 macrophages, leads to reduced tumor growth and enhanced M1 macrophage activation." (PMID 41736026, 2026). "As we have reviewed thus far, there is abundant evidence to support targeting of ATF5, CEBPB and CEBPD individually for therapeutic treatment of gliomas and an array of other cancer types." (PMID 36831248, 2023). "As a result, CEBPD mRNA levels increased along with tumor grades and became significantly overexpressed in GBMs than in normal and low-grade gliomas (LGG; P < 0.05, Tukey HSD ANOVA)." (PMID 37059730, 2023). "Recently, we demonstrated that CEBPD facilitates glioma stem cell formation by regulating stemness genes and elevates ATP-binding cassette subfamily A member 1 expression in temozolomide- (TMZ-) resistant GBM cells." (PMID 36035213, 2022). "CEBPD also regulates the stemness of glioma cells by activating platelet-derived growth factor subunit A (PDGFA) expression due to inflammatory stimulation." (PMID 36153549, 2022). "In bladder cancer and glioma, CEBPD plays an oncogenic role by increasing drug resistance and cancer stemness." (PMID 33436575, 2021). "Glioma GEO datasets showed that CEBPD messenger RNA (mRNA) levels are higher in GBM tissues than in normal brain tissues." (PMID 33436575, 2021). "Taken together, our results suggest CEBPD as a therapeutic target to block certain actions of TMZ-resistant glioma and glioma stemness." (PMID 33436575, 2021). "Recent evidence demonstrates a critical role for CEBPD in glioma stemness due to PDGFA expression in response to inflammatory cytokine treatment." (PMID 33436575, 2021). "This study found that the expression of CEBPD in glioma tissue was significantly higher than that in normal brain tissue." (PMID 32997416, 2020). "This study shows that CEBPD is highly expressed in glioma tissues and cells, and the TCGA database search revealed that CEBPD expression was negatively correlated with patient survival." (PMID 32997416, 2020). "Compared with HA cells, CEBPD expression in glioma cells was significantly increased, and CEBPD knockdown significantly inhibited the capacities for migration, invasion, and VM in glioma cells." (PMID 32997416, 2020). "In conclusion, this study found that the UBE2I/PUM2/CEBPD/DSG2 played crucial roles in regulating glioma VM." (PMID 32997416, 2020). "This study confirmed that CEBPD promoted the expression of DSG2 by transcription in glioma cells, thereby promoting the capacities for migration, invasion, and VM in glioma cells." (PMID 32997416, 2020). "Compared with the NC group, UBE2I knockdown, PUM2 overexpression, and CEBPD knockdown significantly inhibited the capacities for migration, invasion, and VM in glioma cells." (PMID 32997416, 2020). "In this study, by analyzing the database and experimental results, it was found that PUM2 can regulate the VM of glioma cells by binding CEBPD mRNA." (PMID 32997416, 2020). "We found that the expression of PDGFA was significantly higher in glioma samples and was correlated with the CEBPD expression levels in these glioma samples." (PMID 31300060, 2019). "We also found that the expression level of PDGFA significantly correlated with the expression level of CEBPD in these glioma samples." (PMID 31300060, 2019).
glioma (continued). "The glioma tissue microarrays were used for CEBPD and PDGFA expression by immunohistochemistry staining." (PMID 31300060, 2019). "In this study, we have demonstrated that IL-1β-induced CEBPD promotes glioma stemness in U373MG, T98G, and PT#3-spheroid cells by elevating PDGFA expression." (PMID 31300060, 2019). "Taken together, these data suggest that the expression of PDGFA is increased in glioma and is correlated with CEBPD expression." (PMID 31300060, 2019). "Our data demonstrate a novel function of CEBPD, which promotes glioma stem cell spheroid formation under the inflammatory environment." (PMID 31300060, 2019). "We further demonstrate that PDGFA is responsive to CEBPD induction in glioma spheroid cells, and CEBPD regulates PDGFA transcription by binding to the PDGFA promoter region." (PMID 31300060, 2019). "The potential biological functions of CEBPD for glioma was explored." (PMID 37059730, 2023). "The protein levels of CEBPD in glioma tissues were further investigated." (PMID 37059730, 2023). "In this manuscript, we focused on stem cell transcription factors and ABC transporters in TMZ-treated glioma to establish whether CEBPD affects cancer stemness and drug resistance in TMZ-treated glioma." (PMID 33436575, 2021). "In summary, we have found that this novel role of CEBPD may represent a clinical target for treating TMZ-resistant glioma." (PMID 33436575, 2021). "In addition, CEBPD knockdown inhibited the capacities for migration, invasion, and VM in glioma cells, and detected that it plays a procancer role in gliomas." (PMID 32997416, 2020). "CEBPD can also maintain the stemness of glioma stem cells by promoting PDGFA expression." (PMID 32997416, 2020). "However, the functions of CEBPD in glioma and inflammation-induced GSC stemness remain to be clarified." (PMID 31300060, 2019). "In the future, we will continue investigating how CEBPD regulates PDGFRA expression in glioma." (PMID 31300060, 2019). "Our observations thus favor the model of CEBPD function promoting tumor growth in glioma." (PMID 31300060, 2019). "Furthermore, we examined the protein expression of PDGFA and CEBPD in tissue arrays of human glioma samples by immunohistochemical analyses." (PMID 31300060, 2019). "Additionally, we demonstrate that IL-1β can induce CEBPD transcription and expression in glioma cells, which, in turn, promotes glioma stemness." (PMID 31300060, 2019). "In addition, the analysis of the Repository of Molecular Brain Neoplasia Data (REMBRANDT), The Cancer Genome Atlas (TCGA) data combing GBM and LGG expression, and the Chinese Glioma Genome Atlas (CGGA) databases supports that CEBPD is more highly expressed in GBM than in normal and LGGs." (PMID 37059730, 2023). "However, the function of CEBPD in glioma stem cell spheroid formation remains less well understood." (PMID 31300060, 2019). "Genes common to the top 5 activated pathways include POSTN, MMP9, CEBPB, CEBPD, and IGFBP5, which reportedly participate in glioma growth, invasion, and immunosuppression." (PMID 35814469, 2022). "Stem cell transcription factors (SOX2, OCT4, and NANOG) and ABCA1 are responsive to regulation by CEBPD, which directly binds to the promoter regions of those genes in glioma spheroid cells and TMZ-treated glioma cells." (PMID 33436575, 2021). "In summary, this study first discovered the abnormal expression of UBE2I, CEBPD, PUM2, and DSG2 in glioma tissues and cells." (PMID 32997416, 2020). "And we found that the CEBPD/DSG2 axis regulates the capacities for migration, invasion, and VM in glioma cells." (PMID 32997416, 2020). "CEBPD overexpression promotes the transcriptional expression of DSG2, which in turn promotes the capacities for migration, invasion, and VM in glioma cells." (PMID 32997416, 2020). "CEBPD knockdown inhibited the transcriptional regulation of the DSG2, thereby inhibiting the capacities for migration, invasion, and VM in glioma cells." (PMID 32997416, 2020).